IL6 (interleukin 6)
Diseases named in the same sentence as IL6 in open-access papers (continued):
Sharing a sentence is not in itself a finding about the gene and the disease.
Airway obstruction (31 papers, 2008 to 2026). Obstruction of conducting airways of the lung. "Our population‐based cohort study links VOCs‐expanded LYM to elevated obstructive lung disease risk, with exposed individuals showing higher IL‐6 and IL‐17A levels." (PMID 41190786, 2026). "Herfs M reported that anti-IL-6 therapy in vivo significantly reduced epithelial hyperplasia and squamous metaplasia which is associated with airway obstruction in patients with COPD and is a risk factor for tumor transformation and epithelial remodeling." (PMID 32280354, 2020). "Two fatal cases in 19-month-old toddlers, occurring within half a day of symptom onset, were associated with extensive airway obstruction and remarkably high levels of cytokines IL-6 and IL-8 in the bronchi." (PMID 31771554, 2019). "In hierarchical models, the significant association of depressive symptoms with pulmonary obstruction was reduced by the presence of IL-6 and CRP." (PMID 23676005, 2013). "Accordingly, interior decorative VOCs‐associated obstructive lung diseases were potentially mediated by the elevation of LYM and regulated by IL‐6 and IL‐17A." (PMID 41190786, 2026). "A population-based study revealed that elevated levels of inflammatory biomarkers (IL-6 and CRP) contributed to the association of depressive symptoms with pulmonary obstruction." (PMID 35371847, 2022). "Previous studies have shown that IL-6 and IL-8 were increased in COPD patients, and presented strong associations with airway obstruction and lung function." (PMID 35550579, 2022). "Serum levels of ROM were significantly associated with the degrees of airway obstruction, WBC counts, neutrophil counts, IL-6, and severe exacerbations." (PMID 27776186, 2016). "In lung samples from patients with CF, IL-8 and IL-6 levels were elevated and correlated with airway obstruction." (PMID 26485688, 2015). "Thirdly, serum levels of IL-6 and CRP were also found to be associated with FEV1 and FEV1/FVC measures of pulmonary obstruction." (PMID 23676005, 2013). "Our study extends these findings by indicating that a combination of high IL-6 and high CRP as well as a combination of high inflammation and depressive symptoms were associated with mounting levels of pulmonary obstruction." (PMID 23676005, 2013). "Moreover, the cohort study associates VOCs‐expanded lymphocytes with increased risks of obstructive lung diseases, where exposed individuals show elevated IL‐6 and IL‐17A levels, correlating with VOC concentrations and lymphocyte proportions." (PMID 41190786, 2026). "In addition, IL-17A can act with IL-6 to induce MUC5AC, and PM excessively regulates the expression of MUC5AC, causing excessive mucus production in the airways and exacerbating airway obstruction." (PMID 35837279, 2022). "Similarly, IL-6, a key pro-inflammatory cytokine, plays a central role in driving systemic inflammation and immune responses, contributing to the formation of bronchial casts and airway obstruction in PB." (PMID 40800599, 2025). "Despite not having obstructive lung disease, there may still be an element of underlying inflammation (IL6 and IL8) as a result of the AATD." (PMID 37509640, 2023). "Our mediational analyses indicated a strong association of depressive symptoms with spirometric measures of pulmonary obstruction independent of conventional risk factors, but the significance of this association was reduced by the addition of IL-6 and CRP into the hierarchical model." (PMID 23676005, 2013). "Our study indicates that higher levels of IL-6 and CRP combine to produce greater pulmonary obstruction and depressive symptoms." (PMID 23676005, 2013). "This is in agreement with the results obtained in two recent population-based studies, as well as clinical observations of increased IL-6 and CRP levels in clinically stable patients with airway obstruction compared to healthy smoker controls." (PMID 23676005, 2013).
Airway obstruction (continued). "The lack of a relationship between IL-6 and bone turnover biomarkers in our study mirrors previous studies but may be a result of the relatively mild airways obstruction of our patients and the small population size." (PMID 21812978, 2011). "We observed negative correlations between IL-6 and FVC% (r= 0.238, p = 0.033), and between NLR and the FEV1/ FVC ratio (r = −0.199, p = 0.048), suggesting an impact of inflammatory status on both lung volumes and airway obstruction." (PMID 41010685, 2025).
ankylosing spondylitis (31 papers, 2009 to 2026). An autoimmune chronic inflammatory disorder characterized by inflammation in the vertebral joints of the spine and sacroiliac joints. "Despite the high association with ASDAS disease scores, the combined IL-6 + LRG-1 score in ankylosing spondylitis showed little apremilast-induced pharmacodynamic effect." (PMID 31953524, 2020). "Moreover, both conditions share key aspects of immune regulation, notably elevated T-cell-mediated responses and inflammatory cytokines like TNFα, IL-6, and IL-1β, reflecting an increased cardiovascular disease risk in ankylosing spondylitis patients." (PMID 39131703, 2024). "High serum levels of IL-6 may also be associated with ankylosing spondylitis in young people, which is characterized by intense joint pain, stiffness, weakness, marasmus and apocleisis." (PMID 28291252, 2017). "For example, in patients with ankylosing spondylitis, treatment with NSAIDs significantly reduced serum levels of IL-6, IL-17, and TNF-α." (PMID 41010614, 2025). "In ankylosing spondylitis patients, IL-6 and LRG-1 were identified as biomarkers with concordance to disease severity." (PMID 31953524, 2020). "Extensive serum biomarker multiparametric analyses in golimumab-treated patients with ankylosing spondylitis demonstrated few correlations with disease activity or MRI changes; IL-6 weakly correlated with radiographic progression." (PMID 28031053, 2016). "Interestingly, other authors observed that Infliximab treatment decreases IL6 serum levels in patients with ankylosing spondylitis, and this depletion correlated with improvement in disease activity and bone mineral density." (PMID 38449853, 2024). "In an ankylosing spondylitis mouse model, IAA reduced inflammation by suppressing TNF-α, IL-6, IL-17A, and IL-23, while enhancing the expression of IL-10." (PMID 39759289, 2024). "Prior studies have demonstrated that ANXA2 upregulates the expression of IL-6, which subsequently activates the ERK pathway and promotes the development of ankylosing spondylitis (AS)." (PMID 37828081, 2023). "Based upon the observations in cultured cells, rodents, and patients with ankylosing spondylitis of reduced inflammation after exposure to heat stress, we further hypothesized that leg HT would reduce the plasma levels of interleukin 6 (IL‐6) and tumor necrosis factor alpha (TNF alpha)." (PMID 33369253, 2021). "In the ankylosing spondylitis cohort, we discovered robust positive correlations of the disease-centric biomarkers LRG-1 and IL-6 with clinical severity." (PMID 31953524, 2020). "Treatment efficacy was evaluated by use of the Bath Ankylosing Spondylitis Activity Index (BASDAI) score, and serum TNF-α and IL-6 levels were measured pre and post-treatment." (PMID 26245191, 2015). "In patients with ankylosing spondylitis, curcumin significantly increases the number of Tregs, enhances the expression of transforming growth factor-β (TGF-β) and interleukin-10 (IL-10), and suppresses interleukin-6 (IL-6) levels." (PMID 41458964, 2025). "IL-6 and LRG-1 were identified as biomarkers with concordance to ankylosing spondylitis severity." (PMID 31953524, 2020).
arteriosclerosis (31 papers, 2009 to 2025). A vascular disorder characterized by thickening and hardening of the walls of the arteries. "Our result suggests that ET-1 and its link with subclinical arteriosclerosis are potentially driven by low-grade inflammation as depicted by the association with interleukin-6 in the black female cohort." (PMID 26823980, 2015). "Thirdly, GDF15 exhibited incremental value when compared to AOPP and IL-6 in the identification of arteriosclerosis among patients with OSA." (PMID 38378599, 2024). "It exhibited superior accuracy in identifying arteriosclerosis compared to clinical risk factors and other serum biomarkers, such as AOPP and IL-6." (PMID 38378599, 2024). "Among these, GDF15 exhibited an independent association with arteriosclerosis even after adjusting for age, gender, body mass index, SBP, FBG, smoking, AHI, AOPP, and IL-6 in Model 5 (OR [95%CI] = 1.46 (1.21–1.78); p < 0.03)." (PMID 38378599, 2024). "Evidence also suggests that IL-6 contributes to the development of athero-/arteriosclerosis through its chronic low-grade inflammatory effects." (PMID 38378599, 2024). "This study verified the independent and incremental value of GDF15 in identifying arteriosclerosis in OSA patients, surpassing clinical risk factors and other serum biomarkers such as AOPP and IL-6." (PMID 38378599, 2024). "Meanwhile, bioactive substances secreted by adipose tissue, such as angiotensinogen, IL-6 and TNF-α, are associated with changes in vascular inflammation and arteriosclerosis, leading to increased blood pressure." (PMID 35937205, 2022). "The results showed that plasma IL-6 and APN were two important risk factors for subclinical arteriosclerosis." (PMID 32548044, 2020). "IL-6 is a pro-inflammatory cytokine that has been reported in chronic inflammatory diseases such as cancer, arteriosclerosis, and advancing age8, 10–12." (PMID 28484271, 2017). "Raloxifene also decreases inflammatory cytokines such as TNF-α, IL-6, and MCP-1 that cause arteriosclerosis." (PMID 26345606, 2015). "Our result suggests that ET-1 and its link with subclinical arteriosclerosis are potentially driven by low-grade inflammation as depicted by interleukin-6 in the black female cohort." (PMID 26823980, 2015). "Additionally, GDF15 exhibited greater incremental value compared to AOPP or IL-6 in the detection of arteriosclerosis in patients with OSA." (PMID 38378599, 2024). "Moreover, inflammation, for which IL-6 is a key mediator, is a major driving mechanism of accelerated arteriosclerosis." (PMID 37239465, 2023). "Given these previous findings, the Per2 mutation-induced increase in plasma IL-6 may be caused not only by adiposity-triggered inflammation but also by decreased REV-ERBα expression in macrophages, leading to modification of arteriosclerosis." (PMID 28499924, 2017). "Consequently, we hypothesized that IL-6 may play a role in the identification of arteriosclerosis in patients with OSA." (PMID 38378599, 2024). "Moreover, IL-6 promotes vascular inflammation and damage and could potentially be a therapeutic target for the treatment of accelerated arteriosclerosis in SLE." (PMID 33669022, 2021). "Meanwhile, the abnormal activation of the IL6/JAK/STAT3 pathway can upregulate VCAM-1, accelerate endothelial cell damage, and promote arteriosclerosis." (PMID 40809841, 2025). "Previous researches had shown the connections between IL-6 and arteriosclerosis in an animal study, AOPP and arteriosclerosis in healthy individuals, and GDF15 and arteriosclerosis in the general population." (PMID 38378599, 2024). "The results showed that AOPP, IL-6, and GDF15 are all positively correlated with AHI and PWV_ES, which illustrated that the serum biomarkers are not only related to OSA but also to arteriosclerosis." (PMID 38378599, 2024). "In this investigation, the levels of serum biomarkers AOPP, IL-6, and GDF15 were found to be higher in individuals with OSA and arteriosclerosis compared to those with OSA only." (PMID 38378599, 2024).
arteriosclerosis (continued). "Firstly, AOPP, IL-6, and GDF15 levels were observed to be elevated in patients with OSA and arteriosclerosis in comparison to those with OSA alone." (PMID 38378599, 2024). "The results revealed that AHI, AOPP, IL-6, and GDF15 were significant predictors of arteriosclerosis." (PMID 38378599, 2024). "This study is notably the first to investigate the incremental value of AOPP, IL-6, and GDF15 in detecting arteriosclerosis within the OSA population." (PMID 38378599, 2024). "HASMC cells are known to produce inflammatory cytokines involving IL-6, IL-1β, and TNF-α during arteriosclerosis activity." (PMID 33841150, 2021). "Plasma APN, PAI-1, IL-6 and TNF-α levels can be used as monitoring indicators of intracranial and extracranial arteriosclerosis." (PMID 32548044, 2020). "The level of plasma APN in the intracranial and extracranial arteriosclerosis group was significantly lower than that in the control group, and the plasma levels of PAI-1, TNF-α and IL-6 were significantly higher than those in the control group." (PMID 32548044, 2020). "Herein, the current study tried 1) to assess the predictive value of AOPP, IL-6, and GDF15 in relation to arteriosclerosis in patients with OSA; and 2) to examine the incremental value of AOPP, IL-6, and GDF15 in identifying arteriosclerosis in patients with OSA." (PMID 38378599, 2024). "Therefore, we used sequential nested models by adding AHI, AOPP, IL-6 and GDF15 sequentially for predicting arteriosclerosis in OSA patients." (PMID 38378599, 2024). "Additionally, in patients with OSA, the combination of AHI, AOPP, IL-6, and GDF15 yielded the highest AUC (0.87 [0.79–0.95]), demonstrating a sensitivity of 92.9% and specificity of 77.6% in identifying arteriosclerosis." (PMID 38378599, 2024). "In addition to pro-inflammatory cytokines such as TNF-α, IL-1β, IL-6, and MCP-1, chemokines such as macrophage migration inhibitory factor and CXCL12 play an important role in the initiation and the progression of arteriosclerosis." (PMID 36670934, 2022). "In previous studies, PC was found to reduce the mRNA expressions of TNF-α and IL-6 and to combat chronic nonbacterial prostatitis (a male disease) and arteriosclerosis." (PMID 34832910, 2021). "In coincubated B cells, the expression of IL-6 and IFN - γ also increased significantly, which may be the possible mechanism of CXCR5-induced arteriosclerosis." (PMID 33052139, 2020). "In conclusion, we report the novel findings that IL-6 is integral in perpetuating vascular inflammation, dysfunction and damage in MRL-Faslpr and that the MRL-Faslpr mouse model is an excellent tool to study direct and indirect mechanisms of accelerated arteriosclerosis in SLE." (PMID 33669022, 2021). "Moreover, a comprehensive evaluation of clinical risk factors, including age, gender, body mass index, SBP, FBG, and smoking, along with serum biomarkers like AOPP, IL-6, and GDF15, may have a more profound impact on assessing arteriosclerosis in patients with OSA." (PMID 38378599, 2024). "Conversely, elevated levels of AOPP (58 vs. 56 μmol/L, p = 0.01), IL-6 (59 vs. 58 pg/mL, p = 0.03), and GDF15 (101 vs. 94 ng/mL, p = 0.01) were observed in the OSA patients with arteriosclerosis compared to those without arteriosclerosis." (PMID 38378599, 2024). "Compared to OSA patients without arteriosclerosis, those with arteriosclerosis exhibited significantly higher levels of AOPP, IL-6, and GDF15." (PMID 38378599, 2024).
brain tumor (31 papers, 2013 to 2025). "High IL-6 level is a hallmark feature of a number of neurodegenerative diseases including MS, AD, PD and brain tumors." (PMID 32546183, 2020). "In the context of brain tumors, although resident antigen-presenting microglia express TLRs, they are unable to secrete interleukin (IL)-1B, IL-6, or tumor necrosis factor-alpha (TNF-α) to mount an effective innate immune response." (PMID 38256021, 2024). "Hypoxia within a brain tumor stimulated IL-6, which acted upstream as an inducer of autophagy in glioblastoma tumor cells via the IL-6-STAT3-MIR155-3p-CREBRF-CREB3-ATG5 pathway." (PMID 30568636, 2018). "These variables include systemic corticosteroid use and inflammatory markers such as interleukin-6 (IL-6), c-reactive protein (CRP), and erythrocyte sedimentation rate (ESR), which all have associations between elevated levels and poor prognosis in brain tumor patients." (PMID 39840266, 2024). "The use of IL-6 blockade for treatment of CAR T associated neurotoxicity in primary brain tumors is not well described with paucity of literature demonstrating efficacy in improvement in neurological symptoms after IL-6 blockade." (PMID 36874119, 2023). "Moreover, IL-6, IL-8, and TNFα resulted in being overexpressed in the serum of adult and pediatric patients affected by brain tumors." (PMID 35335997, 2022). "Notably, interleukin-6 (IL-6) levels are elevated in the CSF and peripheral blood, in addition to postmortem brain specimens of suicidal patients with brain tumors." (PMID 33371470, 2020). "Like IL-1B also the enhanced expression of TNF might induce IL-6 and subsequently reduce brain tumor growth by enhancing macrophage recruitment." (PMID 30224928, 2018). "Additionally, ACA increased the protein expression levels of the pro-survival signaling cytokines, IL-6 and IL-1α, established cell protectors and survival molecules in brain tumors." (PMID 23833677, 2013). "Variants of NPAS3, a neuronal transcription factor thought to be involved in brain tumor suppression, were found to be associated with 11 of the MetS phenotypes (Fatkg, Leankg, SubQF, TAF, REE, TG, TC, LDL-c, pulse, IL1b and IL-6), suggesting a pleitropic effect." (PMID 23628382, 2013). "In humans, the proinflammatory cytokines IL-1β, IL-6, IL-8, IL-12, GM-CSF and TNF-α have been involved in brain tumor initiation and progression." (PMID 36232813, 2022). "THBO is also said to enhance the inflammatory response in brain tumor patients by reducing TNF-α and IL-6 levels, reducing mean cerebral artery flow, and effectively reducing cerebral artery spasm." (PMID 34790416, 2021). "Elevated CSF IL-10/IL-6 ratio (the thresholds including: ≥0.21, ≥0.72, ≥1, and ≥1.6) could identify PCNSL patients from infection of CNS, other brain tumors, and systemic NHL patients." (PMID 40881684, 2025). "To understand the origins of chemoresistance involving IL-6/STAT3 signaling, we used in vitro co-culture systems to investigate the contribution of microglia as a brain tumor microenvironment cellular source of paracrine cytokines that promotes acquired drug resistance in Group 3 MB." (PMID 35159191, 2022). "The plasma and CSF levels of IL6 and CISD2 in 13 patients with CNS insult, including 11 head injury cases (6 TBI cases, 4 CVA cases, and 1 brain tumor case), 2 SCI cases (1 case each of AIS grade A [complete] and grade B [sensory incomplete] injuries), and 3 healthy controls were examined." (PMID 35453528, 2022). "For comparison, the CSF IL-6 concentration evaluated in 17 patients with non-inflammatory neurological diseases (that is,thirteen with brain tumors and four with neurodegenerative diseases) was 10.4 ± 7.8 pg/ml, with a value ≤10 pg/ml in eleven of seventeen patients." (PMID 23432807, 2013).